MIR8082 (microRNA 8082)
Synonyms: hsa-mir-8082
Gene: MicroRNA gene on chromosome 4 (113,152,282 to 113,152,362, forward strand). Ensembl gene ENSG00000275810.
Homologues: Orthologues: chimpanzee MIR8082 (100% identical).